CHRNB2 (cholinergic receptor nicotinic beta 2 subunit)
Description:
Component of neuronal acetylcholine receptors (nAChRs) that function as pentameric, ligand-gated cation channels with high calcium permeability among other activities. nAChRs are excitatory neurotrasnmitter receptors formed by a collection of nAChR subunits known to mediate synaptic transmission in the nervous system and the neuromuscular junction. Each nAchR subunit confers differential attributes to channel properties, including activation, deactivation and desensitization kinetics, pH sensitivity, cation permeability, and binding to allosteric modulators. CHRNB2 forms heteropentameric neuronal acetylcholine receptors with CHRNA2, CHRNA3, CHRNA4 and CHRNA6, as well as CHRNA5 and CHRNB3 as accesory subunits. Found in two major stoichiometric forms,(CHRNA4)3:(CHRNB2)2 and (CHRNA4)2:(CHRNB2)3, the two stoichiometric forms differ in their unitary conductance, calcium permeability, ACh sensitivity and potentiation by divalent cation. Heteropentameric channels with CHRNA6 and CHRNA4 exhibit high sensitivity to ACh and nicotine and are predominantly expressed in only a few brain areas, including dopaminergic neurons, norepirephrine neurons and cells of the visual system. nAChrs containing CHRNA6 subunits mediate endogenous cholinergic modulation of dopamine and gamma-aminobutyric acid (GABA) release in response to nicotine at nerve terminals (By similarity). Also forms functional nAChRs with other subunits such as CHRNA7:CHRNB2, mainly expressed in basal forebrain cholinergic neurons.
Synonyms: EFNL3; nAChRB2
Tractability: Small molecule: an approved drug acts on it; a structure with a bound ligand is known; a high-quality ligand is known; it has a high-quality binding pocket; it belongs to a druggable protein family. Antibody: UniProt places it where antibodies can reach, with high confidence; its Gene Ontology location is reachable by antibodies, with high confidence; UniProt predicts a signal peptide or a membrane-spanning region. PROTAC: its protein half-life has been measured; a small molecule that binds it is known.
Target class: Ligand-gated ion channel; Ion channel; Nicotinic acetylcholine receptor beta subunit; Nicotinic acetylcholine receptor
Safety:
Unwanted effects reported when the protein is acted on. In parentheses: how it was acted on, where the effect was seen, and who reports it.
smoking addiction (source: ClinPGx)
smoking addiction and smoking cessation (source: ClinPGx)
smoking addiction, and a smoking cessation (source: ClinPGx)
Gene: Protein-coding gene on chromosome 1 (154,567,778 to 154,580,013, forward strand). Ensembl gene ENSG00000160716.
Subcellular location: Synaptic cell membrane; Cell membrane
Pathways (Reactome):
Neuronal System: Highly calcium permeable nicotinic acetylcholine receptors; Highly calcium permeable postsynaptic nicotinic acetylcholine receptors; Highly sodium permeable postsynaptic acetylcholine nicotinic receptors
Gene Ontology:
Molecular function: acetylcholine binding; acetylcholine receptor activity; acetylcholine-gated monoatomic cation-selective channel activity; protein binding; ligand-gated monoatomic ion channel activity; extracellular ligand-gated monoatomic ion channel activity; monoatomic ion channel activity; transmembrane signaling receptor activity
Biological process: acetylcholine receptor signaling pathway; behavioral response to nicotine; cognition; learning; memory; nervous system process; response to hypoxia; response to nicotine; signal transduction; synaptic transmission, cholinergic; visual learning; associative learning; B cell activation; calcium ion transport; central nervous system projection neuron axonogenesis; lateral geniculate nucleus development; locomotory behavior; membrane depolarization; monoatomic ion transmembrane transport; monoatomic ion transport; negative regulation of action potential; optic nerve morphogenesis; positive regulation of B cell proliferation; positive regulation of dopamine secretion; regulation of circadian sleep/wake cycle, REM sleep; and 18 more
Cellular component: acetylcholine-gated channel complex; synapse; external side of plasma membrane; membrane; neuron projection; plasma membrane; plasma membrane raft; presynaptic membrane; synaptic membrane; postsynaptic membrane
Genetic constraint (gnomAD): Loss-of-function variants: 31 observed, 37.5 expected, observed/expected ratio (o/e) 0.83, 90% interval 0.62 to 1.12. The upper end of that interval is the gene's LOEUF score, 1.12, which puts it in group 4 of 6, group 1 being the genes least tolerant of losing a copy. Missense variants: 602 observed, 673.92 expected, observed/expected ratio (o/e) 0.89, 90% interval 0.83 to 0.96. Synonymous variants: 325 observed, 283.95 expected, observed/expected ratio (o/e) 1.14, 90% interval 1.04 to 1.25.
Gene-disease validity (ClinGen):
ClinGen rates the evidence that CHRNB2 causes each of these diseases.
familial sleep-related hypermotor epilepsy (autosomal dominant): Definitive. An instance of sleep-related hypermotor epilepsy that is caused by an inherited genomic modification in an individual.
Homologues: Orthologues: chimpanzee CHRNB2 (100% identical), macaque CHRNB2 (99% identical), pig CHRNB2 (96% identical), rat Chrnb2 (93% identical), dog CHRNB2 (89% identical), mouse Chrnb2 (86% identical), tropical clawed frog chrnb2 (83% identical), zebrafish chrnb2 (79% identical), zebrafish chrnb5b (59% identical). Paralogues in human: CHRNB4 (63% identical), CHRNA4 (48% identical), CHRNA2 (46% identical), CHRNA3 (44% identical), CHRNA6 (44% identical), CHRND (40% identical), CHRNB1 (39% identical), CHRNG (38% identical), CHRNA1 (37% identical), CHRNB3 (37% identical), CHRNA5 (37% identical), CHRNE (35% identical), and 33 more.